TRPV4 (transient receptor potential cation channel subfamily V member 4)
Diseases named in the same sentence as TRPV4 in open-access papers (continued):
Sharing a sentence is not in itself a finding about the gene and the disease.
skeletal dysplasia (50 papers, 2009 to 2026). Any Mendelian diseases that affects growth and development of the skeleton. "It is clinically difficult to clearly distinguish between the various forms of skeletal dysplasia caused by mutations in the TRPV4 gene, but this can be achieved by a combination of gene sequencing, clinical phenotyping and radiological criteria." (PMID 40258774, 2025). "The same phenomenon is also observed in skeletal dysplasia mutations like D333G, where TRPV4 antagonist GSK219 significantly boost neurite growth." (PMID 39333347, 2025). "Of all the skeletal dysplasias associated with mutations in the TRPV4 gene, SMDK has the most similar features to MD." (PMID 40258774, 2025). "This loss-of-function profile contrasts with the classical gain-of-function mechanism reported in most TRPV4-related skeletal dysplasias, suggesting an atypical pathogenic pathway." (PMID 41225599, 2025). "Mutations in TRPV4 lead to a spectrum of disorders, ranging from hereditary motor neuropathies to skeletal dysplasias." (PMID 41225599, 2025). "Heterologous expression studies suggest that both neuromuscular disease- and skeletal dysplasia-causing TRPV4 mutants exhibit normal expression levels but increased channel activity." (PMID 41338459, 2025). "Dominant mutations in the calcium permeable ion channel TRPV4 (transient receptor potential vanilloid 4) typically result in skeletal dysplasia or peripheral neuromuscular disease." (PMID 41263626, 2025). "TRPV4 mutations cause groups of diseases that include skeletal dysplasias, peripheral neuropathies, and osteoarthropathy, and are predominantly mis-sense mutations with specific amino acid substitutions appearing throughout the channel protein." (PMID 38612378, 2024). "To date, over 50 mutations of TRPV4 have been found to be associated with skeletal dysplasia, according to the Human Gene Mutation Database." (PMID 38292178, 2024). "The importance of TRPV4 is apparent in patients harboring TRPV4 mutations, which result in the development of a spectrum of skeletal dysplasias and arthropathies." (PMID 37175575, 2023). "TRPV4 has also been linked to several human congenital disorders, which have been grouped into skeletal dysplasias and neuromuscular disorders." (PMID 36549871, 2023). "One subset of TRPV4 mutations causes different variants of skeletal dysplasias, which encompass a diverse group of more than 200 diseases." (PMID 33467654, 2021). "The TRPV4 mutations linked to skeletal dysplasia were shown to cause a gain of function of the channel." (PMID 34208776, 2021). "Several studies have been reported to explain the pathology of skeletal dysplasia caused by TRPV4 mutations." (PMID 33668763, 2021). "Most strikingly, mutation of the residue at position 183 of TRPV4 can cause a skeletal dysplasia or CMT type 2C depending on the introduced amino acid, with no phenotypic overlap between the cases." (PMID 32443528, 2020). "We discuss the common symptoms between the proband, her father, and her daughter, and compare her phenotype to known TRPV4‐associated skeletal dysplasias." (PMID 30693671, 2019). "Although patient-derived cells are useful models for elucidating the etiology of TRPV4-associated skeletal dysplasia, only a few studies in patient-derived cells have been reported, possibly because of the wide variety of genotypes and phenotypes." (PMID 31463371, 2019). "Gain-of-function TRPV4 variants are associated with other phenotypes varying from severe skeletal dysplasias to peripheral neuropathies." (PMID 31248428, 2019). "Various mutations of TRPV4 associated with skeletal dysplasia have been reported to alter the Ca2+ channel function of TRPV4." (PMID 31463371, 2019). "The mechanism by which TRPV4 protein dysfunction causes disease is still debated, although recent literature poses an explanation for the pathogenesis of TRPV4‐associated skeletal dysplasias." (PMID 30693671, 2019).
skeletal dysplasia (continued). "Patient-derived DPSCs will be useful for further elucidating the pathogenesis of TRPV4-associated skeletal dysplasia." (PMID 31463371, 2019). "In TRPV4-associated skeletal dysplasia, a wide variation in TRPV4 mutations and symptoms have been reported, but there have been only a few patient-derived disease models for etiological investigation." (PMID 31463371, 2019). "Mutations in TRPV4, encoding a calcium-permeable cation channel, give rise to either skeletal dysplasia, sometimes with early lethality, or peripheral neuropathy or a combination of both." (PMID 28842795, 2017). "Mutations in the transient receptor potential cation channel TRPV4 have been found to cause many different forms of skeletal dysplasias (SD)." (PMID 21573172, 2011). "More than 30 different TRPV4 mutations underlying these three skeletal dysplasias have been reported in the literature to date, mutational hotspots have been identified, and some tentative genotype-phenotype correlations made." (PMID 21658220, 2011). "Some of these newly identified genes are well characterized as cartilage-selective and associated with one of a variety of forms of skeletal dysplasia (e.g., TRPV4, COL2A1, COMP, and COL9A3)." (PMID 20046828, 2009). "Embryonic, chondrocyte-specific induction of the mutation using Col2a1-Cre resulted in a skeletal dysplasia affecting the long bones, spine, and craniofacial skeletal elements, consistent with the human skeletal dysplasia phenotypes produced by TRPV4 mutations." (PMID 41574606, 2026). "In addition to hereditary neuromuscular disease, distinct missense mutations of TRPV4 are associated with several forms of skeletal dysplasia." (PMID 41338459, 2025). "Recent analyses of cryo-EM structures suggest that many skeletal dysplasia-causing mutations located outside the ARD may directly influence the TRPV4 pore gate, whereas those in the ARD may impact inter-subunit interactions." (PMID 41338459, 2025). "Mutations in the TRPV4 ion channel can lead to a range of skeletal dysplasias." (PMID 36810131, 2023). "The obvious differences in both resting and activated states confirm functional differences with TRPV4 mutations that may ultimately lead to changes in downstream signaling of the channel, which alter joint development and result in skeletal dysplasias." (PMID 36810131, 2023). "Analysis of transgenic mice expressing mouse mutant Trpv4 (R594H), the same mutation as one of human TRPV4-related skeletal dysplasia, under the control of the cartilage-specific Col2a1 promoter, showed lethal defects of endochondral ossification similar to MD." (PMID 33668763, 2021). "In contrast, skeletal dysplasia mutations are found throughout multiple domains of TRPV4 in regions that may be critical for regulation of ion channel gating." (PMID 33664271, 2021). "TRPV4 mutations also cause skeletal dysplasias through aberrant calcium signaling." (PMID 32581710, 2020). "TRPV4 calcium channel disruptions are associated with a wide variety of skeletal dysplasias." (PMID 32581710, 2020). "The six skeletal dysplasias linked to TRPV4 pathogenic variants vary widely in severity." (PMID 30693671, 2019). "However, Trpv4 transgenic mice expressing the known pathogenic missense mutation p.Arg594His showed a severe skeletal dysplasia that recapitulated abnormalities of metatropic dysplasia in humans." (PMID 29262782, 2017). "The mechanism by which TRPV4 mutation causes skeletal dysplasia is unclear." (PMID 21573172, 2011). "Five more TRPV4 mutations were found to be present in patients from 21 families presenting skeletal dysplasias: K407E, R594S, Q239H, Y591C, and the insertion/duplication L523, and it was later suggested that mutations that caused skeletal dysplasias could also cause neuropathic diseases." (PMID 32481620, 2020).
skeletal dysplasia (continued). "However, a clear distinction between various forms of skeletal dysplasias caused by the transient receptor potential vanilloid 4 (TRPV4) gene is difficult but could be achieved by a combination of gene sequencing, medical and radiological criteria." (PMID 31808622, 2019). "Growing evidence has shown that TRPV4 is involved in numerous physiological functions including body osmoregulation and noxious mechanical and thermal sensation, and mutation in the TRPV4 gene is known to cause skeletal dysplasia and neurodegenerative diseases." (PMID 26973533, 2016). "The TRPV4 skeletal dysplasias are characterized by short stature, short limbs with prominent large joints, and progressive scoliosis." (PMID 41574606, 2026). "Whereas neuromuscular disease-causing mutations cluster in the TRPV4-ARD, mutations associated with skeletal dysplasia occur throughout the protein." (PMID 41338459, 2025). "Functional assays demonstrated a marked reduction in TRPV4 channel activity, indicating a hypofunctional mechanism that contrasts with the canonical gain-of-function effects observed in most TRPV4-related skeletal dysplasias." (PMID 41225599, 2025). "The most studied TRPV4 mutant-related heritable diseases are generally classified into two major categories: peripheral neuropathies and skeletal dysplasia." (PMID 39333347, 2025). "Our findings provide potential therapeutic targets for developing treatments for TRPV4-mediated skeletal dysplasias." (PMID 36810131, 2023). "Our data suggest the TRPV4 skeletal dysplasias represent a continuum of severity with areas of phenotypic overlap, even within the same family." (PMID 21658220, 2011). "Strikingly, neuromuscular disease- but not skeletal dysplasia-causing mutations disrupt TRPV4-RhoA binding and the capacity of TRPV4 to inhibit RhoA activation." (PMID 41338459, 2025). "This deviates from the typical gain-of-function paradigm observed in most TRPV4-related skeletal dysplasias and may explain the relatively milder phenotype in our case." (PMID 41225599, 2025). "Other future experiments could activate the channel osmotically or with mechanical loading to investigate additional differences in TRPV4 function leading to skeletal dysplasias during development." (PMID 36810131, 2023). "Our results suggest that skeletal dysplasias may be, at least in part, resulting from improper chondrocyte hypertrophy downstream of altered TRPV4 function." (PMID 36810131, 2023). "Mutations in transient receptor potential vanilloid 4 (TRPV4), a non-selective cation channel, can lead to varying degrees of skeletal dysplasia, including moderate autosomal-dominant brachyolmia and severe metatropic dysplasia." (PMID 36810131, 2023). "Pathogenic variants of TRPV4 can cause both skeletal dysplasias and neuromuscular disorders with these phenotypes not always presenting independently of one another." (PMID 30693671, 2019). "Recently, it has been reported that TRPV4 could modulate Ca2+ influx and muscle fatigue and is furthermore involved in skeletal dysplasia." (PMID 23536811, 2013). "Thus, while other factors are at play, our results are consistent with the increased TRPV4 basal activity being a critical determinant of the severity of skeletal dysplasia." (PMID 21573172, 2011). "It was revealed that mutations in TRPV4 disrupted the bone morphogenetic protein (BMP) signaling pathway in iPSC-derived chondrocytes and blocked formation of hypertrophic chondrocytes providing potential targets for drug development for TRPV4-associated skeletal dysplasias." (PMID 38926793, 2024). "In addition, several TRPV4 mutations that cause skeletal dysplasia do not elicit higher intracellular Ca2+ concentrations." (PMID 38292178, 2024). "However, this phenomenon has not been reported in families with TRPV4-associated skeletal dysplasia." (PMID 36118854, 2022).
skeletal dysplasia (continued). "In addition, the disruption of the folding-sensitive region of TRPV4 could be a therapeutic option for diseases in which TRPV4 increases its activity such as pain and skeletal dysplasias." (PMID 31783610, 2019). "Four mutations in two of the six N-terminal ankyrin repeats of TRPV4 have also recently been shown to cause a spectrum of late-onset neuromuscular diseases but not skeletal dysplasia, indicating that SD and these neuromuscular diseases arise by different mechanisms." (PMID 21573172, 2011). "Our results are consistent with the chronic basal open probability of the mutant TRPV4 being a key, though probably not the only, determinant of the severity of skeletal dysplasia in human." (PMID 21573172, 2011).
cardiovascular diseases (16 papers, 2015 to 2025). "In summary, TRPV4 plays a unique role in fibroblast activation and matrix remodeling, and the dysregulated ECM remodeling caused by TRPV4 dysfunction is closely related to a variety of cardiovascular diseases and fibrosis." (PMID 39425532, 2024). "However, although TRPV4′s involvement in cardiovascular diseases is well-documented, the mechanisms underlying TRPV4-mediated passive cardiac injury remain incompletely understood." (PMID 40863131, 2025). "Indeed, TRPV4 channels have surfaced as particularly pivotal conduits for dynamic Ca2+ signaling in the endothelium and altered TRPV4 signaling has been implicated in progressive cardiovascular disease." (PMID 35492608, 2022). "In this manuscript, we provide an overview of TRPV4 channel implications in cardiac physiology and discuss the potential of the TRPV4 channel as a therapeutic target against cardiovascular diseases." (PMID 37371124, 2023). "Further investigations are undoubtedly needed to fully understand TRPV4’s role in cardiac contractility in human cardiovascular diseases." (PMID 37371124, 2023). "Recent implication of Ca2+-permeable TRPV4 channels in cardiovascular disease has focused attention on their specific impact on vascular signaling and their potential as targets for therapeutic intervention." (PMID 32235694, 2020). "TRPV4 has primarily been studied as a target for cardiovascular disease treatment." (PMID 37369706, 2023). "For the predicted target, Bile acid receptor and TrpV4 are the targets for cardiovascular disease." (PMID 33482800, 2021). "However, identification and functional chacterization of both Piezo1 and TRPV4 throughout the vascular endothelium would be needed before considering therapeutics for cardiovascular diseases directed against these ion channels." (PMID 33298523, 2021). "Our findings implicate that pharmacological activation of TRPV4 may serve as an effective and complementary strategy to the management of cardiovascular diseases." (PMID 27191895, 2016). "Potentially, pharmacological modulation of BP via TRPV4 or other RN1734 sensitive ion channels could be useful in the treatment of cardiovascular disease; however, the widespread distribution of TRPV4 ion channels could limit their practical usefulness." (PMID 25954200, 2015). "Potentially, in the future, the TRPV4 channel, or the TRPV4–KCa coupling mechanism, may serve as a therapeutic target for treatment of cardiovascular disease." (PMID 25954200, 2015). "TRPV4 channels are pivotal conduits for dynamic Ca2+ signaling in the arterial endothelium, and their capacity to generate and relay Ca2+ signals may be altered in cardiovascular disease." (PMID 35492608, 2022). "HSYA could increase calcium ions via TRPV4 channels, activate eNOS and its phosphorylation via protein kinase A, and promote NO production, thereby relaxing blood vessels, indicating that HSYA is a candidate for the treatment of cardiovascular diseases caused by aging." (PMID 36430769, 2022).
peripheral neuropathy (16 papers, 2007 to 2025). A disorder affecting the peripheral nervous system. "We report a patient with MD caused by a novel missense mutation in TRPV4, who possessed a mixed phenotype of both abnormal skeletal development and peripheral neuropathy." (PMID 40258774, 2025). "The TRPV4 gene mutations have generated osteoarthropathy, skeletal dysplasia and peripheral neuropathies, manifesting as a variable combination of skeletal, motor and neuronal symptoms, including pain." (PMID 36670886, 2022). "Investigating how TRPV4 mutations cause peripheral neuropathy provides an opportunity to understand the molecular events linking an ion channel and Ca2+ homeostasis to the process of neurodegeneration." (PMID 32471994, 2020). "Therefore, kinins sensitize TRPV4 and cause mechanical hyperalgesia in paclitaxel-induced peripheral neuropathy through PKCε activation." (PMID 36670886, 2022). "TRPV4’s participation has also been investigated in different preclinical models of pain and nociception induced by inflammatory and neuropathic pain, and this receptor was implicated as a contributor to the etiology of chemotherapy-induced peripheral neuropathy." (PMID 38730655, 2024). "Most studies investigating TRPV4’s involvement in CIPN-induced nociception have reported paclitaxel, thalidomide, and vincristine as causing neural injury, leading to painful peripheral neuropathy." (PMID 38730655, 2024). "In line with that, TRPV4 antagonists and knockdown of TRPV4 levels reduce nociception in chemotherapy-induced peripheral neuropathy (CIPN)." (PMID 39517820, 2024). "Many studies revealed that the administration of a TRPV4 antagonist and TRPV4 knockdown diminishes nociception in chemotherapy-induced peripheral neuropathy (CIPN)." (PMID 38730655, 2024). "Toll-like receptors (TLR-1, TLR-2, and TLR-4) and the transient receptor potential family of ion channels (TRPV1 and TRPV4) have been discovered, demonstrating their active role in chemotherapy-induced peripheral neuropathy." (PMID 35956877, 2022). "The paclitaxel-induced peripheral neuropathy model was first used to evaluate the TRPV4 involvement in nociceptive behavior responses to mechanical and hypotonic stimulation of the hind paw." (PMID 36670886, 2022). "The results of this study suggest that local activation of TRPV4 could be an attractive alternative therapeutic intervention after peripheral nerve injury, although there are a lot of reports showing that gain-of-function mutation of TRPV4 causes peripheral neuropathies in humans." (PMID 33247229, 2020). "The interplay of TRPV4 with microtubule cytoskeleton also appears on a behavioural level, where alteration of microtubule dynamics by Taxol induces a TRPV4-dependent painful peripheral neuropathy." (PMID 20657843, 2010). "Thus, subsequently, a paclitaxel-induced peripheral neuropathy model was used to investigate the TRPV4 expression in the DRG neurons and its relation to nociceptive behavior due to the TLR-4 activation and the production of TNF-α." (PMID 36670886, 2022). "Therefore, α2β1 integrin and TRPV4 interaction transduces mechanical allodynia in the injured sensory neurons of the alcohol-induced peripheral neuropathy model." (PMID 36670886, 2022). "TRPV4 inhibition has also been shown to be protective in rodent models of chemotherapy-induced peripheral neuropathy, suggesting that TRPV4 antagonists may have utility in peripheral neuropathies of diverse etiologies." (PMID 32471994, 2020). "However, this was the only study that evaluated the TRPV4 role in ddC-induced peripheral neuropathy but introduced the perspective that the TRPV4 blockage could be a treatment approach." (PMID 36670886, 2022). "Furthermore, in models of painful peripheral neuropathy induced by vincristine chemotherapy, alcoholism and diabetes, mechanical hyperalgesia was attenuated by intrathecal injection of TRPV4 antisense oligodeoxynucleotides, and the similar effect was also observed in TRPV4 knockout mice." (PMID 19208258, 2009).